RBM24 (RNA binding motif protein 24)
Diseases named in the same sentence as RBM24 in open-access papers (continued):
Sharing a sentence is not in itself a finding about the gene and the disease.
Hirschsprung disease (2 papers, 2020 to 2021). Hirschsprung disease (HSCR) is a congenital intestinal motility disorder that is characterized by signs of intestinal obstruction due to the presence of an aganglionic segment of variable extent in the terminal part of the colon. "Although a previous study has reported that RBM24 presents a certain correlation with Hirschsprung's disease, little is known about the biological function of RBM24 in intestinal tumours." (PMID 34709758, 2021).
liver cancer (2 papers, 2021 to 2022). An epithelial or non-epithelial malignant neoplasm that arises from the liver. "Indeed, recent studies indicate that RBM24 shows reduced expression in liver cancer cell lines (HepG2, Hep3B, and Huh7) and exerts tumor-suppressive functions in HCC cells through several post-transcriptional mechanisms." (PMID 35406615, 2022). "RBM24 inhibits liver cancer cell growth and progression and induces sorafenib sensitivity." (PMID 34804951, 2021). "RBM24 inhibits nuclear translocation of CTNNB1 in liver cancer cells." (PMID 34804951, 2021).
muscular dystrophies (2 papers, 2016 to 2020). "It will be interesting to explore the possible correlation between the Rbm24 protein expression and muscular dystrophy and whether Rbm24 is dysfunctional in DM1 patients in the future." (PMID 33042276, 2020). "One attracting issue is whether Rbm24 plays a role in muscular dystrophy." (PMID 33042276, 2020).
prostate carcinoma (2 papers, 2020 to 2022). A carcinoma that arises from epithelial cells of the prostate gland. "A recent study indicates that in prostate cancer, the microRNA miR-106a-5p promotes cell proliferation by inhibiting Rbm24 expression, and overexpression of wild-type Rbm24 is able to inhibit tumorigenesis." (PMID 32806768, 2020). "While RBM24 is mostly accumulated in the nucleus of testis cancer cells, it is moderately present in the nucleus of a fraction of cells in some cases of lung, ovarian and prostate cancers, but is absent in the nucleus of other cancers." (PMID 35406615, 2022).
adenoma (1 paper, 2021). A neoplasm arising from the epithelium. "During the construction process of our Rbm24 knockout mouse model, we unexpectedly detected a certain number of adenomas within the intestine of tamoxifen‐induced Rbm24‐knockout mice." (PMID 34709758, 2021). "At 6 months after Rbm24 knockout, an enlargement of the colon in mice was observed; the colorectal segment was strikingly longer than that of WT mice and the number of adenomas increased significantly." (PMID 34709758, 2021).
cervical cancer (1 paper, 2022). A primary or metastatic malignant neoplasm involving the cervix. "According to THPA, the highest expression of RBM24 is observed in HNSCC, followed by cervical cancer, although we have not seen its use as a diagnostic tool." (PMID 36142875, 2022).
colon adenocarcinoma (1 paper, 2021). "RBM24 expression level in colon adenocarcinoma (COAD) and rectum adenocarcinoma (READ) was inversely correlated with its promoter methylation level." (PMID 34709758, 2021).
colorectal cancer (1 paper, 2021). A primary or metastatic malignant neoplasm that affects the colon or rectum. "Colorectal cancer cells overexpressing or silencing RBM24 were established." (PMID 34709758, 2021).
gastric cancer (1 paper, 2022). A primary or metastatic malignant neoplasm involving the stomach. "However, in gastric cancer, RBM24 expression seems to be associated with tumor cell migration or invasion." (PMID 35406615, 2022). "Given the possible link between RBM24 and ZEB1 in gastric cancer, it will be also of interest to examine whether and how RBM24 modulates ZEB1 expression and EMT in lung cancer." (PMID 35406615, 2022).
glioblastoma multiforme (1 paper, 2022). "Indeed, TCGA database showed that RBM24 is down-regulated in several types of cancers, including glioblastoma multiforme (GB) and brain lower grade glioma (LGG)." (PMID 36478739, 2022).
intestinal tumours (1 paper, 2021). "In this study, our data indicated that Rbm24 was significantly downregulated in intestinal tumour of Apcmin/+ mice." (PMID 34709758, 2021).
lentivirus infection (1 paper, 2017). Virus diseases caused by the Lentivirus genus. "A reduction in Stk38 as well as Rbm24 was observed 2 days after shStk38 lentivirus infection." (PMID 28322254, 2017).
lung carcinoma (1 paper, 2022). "RBM24 may play a role in lung cancer development, but how it functions to modulate progression of this type of cancer remains unclear." (PMID 35406615, 2022). "By contrast, another study indicates that RBM24 protein shows increased expression in lung cancer tissues in a majority of cases, which may be correlated with a decreased chemosensitivity of lung adenocarcinoma (LUAD) cells and a reduced overall survival rate of patients with NSCLC." (PMID 35406615, 2022). "Due to these discrepancies and the lack of detailed mechanistic analyses, the exact role of RBM24 in lung cancer awaits further functional investigation." (PMID 35406615, 2022).
ovarian carcinoma (1 paper, 2024). A malignant neoplasm originating from the surface ovarian epithelium. "In particular, the up- and down-regulation of RBM24 and ESRP1, respectively, represent a main regulator of EMT in ovarian cancer cells." (PMID 38365970, 2024).
Parkinson (1 paper, 2024). "Our findings identify Notch1 as a direct downstream target of Rbm24, implicating the Rbm24/Notch1 signaling axis in Parkinson-associated olfactory dysfunction." (PMID 39113792, 2024). "Considering that the phenotypes of Rbm24 deletion exhibit Parkinson-like features in the SVZ-OB pathway, this study further explored the relevance of Rbm24/Notch1 signaling in PD." (PMID 39113792, 2024).
tumor (14 papers, 2016 to 2025). "This review provides a comprehensive analysis of recent findings on the implication of RBM24 in cancer and proposes future research directions to delve more deeply into the mechanisms underlying its tumor-suppressive function or oncogenic activity." (PMID 35406615, 2022). "Future studies using clinical samples and appropriate animal models will help to provide insight into the molecular and cellular mechanisms underlying RBM24 function in tumor progression." (PMID 35406615, 2022). "The upregulation of RBM24 can, in turn, repress tumor progression by stabilizing mRNAs encoding tumor suppressor proteins." (PMID 35406615, 2022). "On the contrary, increased expression of RBM24 in other cancers may be associated with cell proliferation and tumor progression, resulting in poor prognosis and low overall survival." (PMID 35406615, 2022). "The protein products of FRZB and RBM24 have tumor suppressive roles in colorectal and other cancers." (PMID 40753397, 2025). "The challenge remains to determine the post-transcriptional mechanisms by which RBM24 modulates gene expression and tumor progression in a context- or background-dependent manner." (PMID 35406615, 2022). "For example, the ncRNA TPRG1-AS1 (tumor protein p63 regulated 1, antisense 1) has been shown to exert a tumor-suppressing property through stabilization of RBM24 expression by sequestrating its inhibitory miR-3659 and miR-4691-5p." (PMID 35406615, 2022). "In several tissues, RBM24 clearly functions as a tumor suppressor, which is consistent with its inhibitory potential on cell proliferation." (PMID 35406615, 2022). "It is possible that RBM24 exerts anti-tumor or pro-tumor activity in a context- or background-dependent manner." (PMID 35406615, 2022). "In functional assays, overexpression of RBM24 inhibits tumor growth in xenografts and suppresses migration and invasion of NPC cells, while knockdown of RBM24 produces the opposite effects, suggesting that it exerts anti-tumor activity in NPC." (PMID 35406615, 2022). "Nevertheless, it remains largely unclear how RBM24 exerts its anti-tumor activity and pro-tumor activity." (PMID 35406615, 2022). "To conclude, RBM24, as a novel tumor inhibitor gene, inhibits the LN metastasis and EMT by the downregulation of the Twist1 in HSCC." (PMID 36213838, 2022). "Most importantly, the probable function of RBM24 was as a tumor inhibitor against the HSCC evolution." (PMID 36213838, 2022). "It seems that RBM24 displays either decreased or increased expression as well as anti-tumor or pro-tumor activity, depending on the cancer type." (PMID 35406615, 2022). "In several cancers, RBM24 functions as a tumor suppressor, and its low expression can lead to tumorigenesis." (PMID 35406615, 2022). "As a tumor suppressor, abnormally high levels of RBM24 expression, induced by drugs, can lead to hepatocyte death." (PMID 36233241, 2022). "RBM24's suppressive actions against the tumor evolution and LN metastasis in HSCC in-vivo were also validated." (PMID 36213838, 2022). "Consistent with its differentiation-promoting function during embryonic development, RBM24 can act as a tumor suppressor to inhibit cell proliferation and tumor growth in several cancers." (PMID 35406615, 2022). "Overexpression of RBM24 prevents tumor cell growth and induces sorafenib sensitivity by indirectly reducing the expression level of p63 mRNA likely through inhibition of β-catenin nuclear translocation." (PMID 35406615, 2022). "Taken together, our findings suggest that RBM24 acts as a tumour suppressor gene in colorectal tumourigenesis." (PMID 34709758, 2021).
tumor (continued). "Considering the association among PI3K/Akt signalling pathway, tumour drug resistance and the regulation of PI3K/Akt signalling pathway by RBM24, we believe that RBM24 is closely related to CRC chemoresistance." (PMID 34709758, 2021). "Taken together, these results show that RBM24 acts as a tumour suppressor gene, suppressing colorectal tumourigenesis." (PMID 34709758, 2021). "RBM24 was significantly elevated in two tumor cell lines (UM-UC-3 and 253 J) but downregulated in one (J82) compared to normal bladder cells." (PMID 34021255, 2021). "Further, qPCR results showed that mRNA expression of PTEN in human CRC tumour tissues was markedly downregulated and positively correlated with mRNA expression of RBM24." (PMID 34709758, 2021). "Western blotting and qPCR analysis revealed that PTEN expression was significantly decreased and positively correlated with RBM24 expression in tumour tissues of RBM24‐knockout mice." (PMID 34709758, 2021). "In mammalian cancers, many oncogenes and tumor suppressors are under the control of RBPs, among which the RBM24 can bind to the AU/U-rich elements in its target mRNAs and regulate the stability of p21 and p63 mRNA transcripts." (PMID 33224130, 2020). "Here, we report the identification of two tumor suppressors, the RNA-binding protein 24 (RBM24) and myogenic differentiation 1 (MYOD1), being two biological targets for miR-M2-5p." (PMID 33224130, 2020). "Another enigma is the significance of Rbm24 and Rbm38 in preventing p63-mediated tumor suppression because they have been shown to destabilize p63 mRNA in overexpression experiments." (PMID 32806768, 2020). "Next, we performed xenograft experiments to show that RBM24 overexpression caused the inhibition of NPC tumorigenesis and conveyed a survival advantage through its propensity to suppress tumor metastasis." (PMID 27584791, 2016). "The tumor growth curves derived from the xenograft experiments indicated that induction of RBM24 expression impeded the growth of NPC cells in nude mice." (PMID 27584791, 2016). "In the present study, we conducted in vitro and in vivo assays, demonstrating that RBM24 had a strong tumor suppressive potential in NPC cells." (PMID 27584791, 2016). "Further studies of RBM24 expression in patient-derived tumor tissues will help to determine its clinical significance in NPC diagnosis and treatment." (PMID 27584791, 2016). "Taken together, our results demonstrate that RBM24 functions as a novel tumor suppressor in NPC by repressing tumorigenicity and invasion." (PMID 27584791, 2016). "The results also showed that RBM24 was significantly downregulated in the tumor tissues compared with non-tumor tissues." (PMID 27584791, 2016). "On the basis of our findings, we propose a model in which RBM24 plays a role as a tumor suppressor through the upregulation of miR-25, which directly targets MALAT1 for degradation." (PMID 27584791, 2016). "However, these correlative data require further experimental validation to determine how RBM24 regulates cell proliferation and tumor metastasis in these cancers." (PMID 35406615, 2022). "These raise the possibility that RBM24 may act either as a tumor suppressor or as an oncogene, functioning in a context- or background-dependent manner." (PMID 35406615, 2022). "There is a possibility that RBM24 displays both anti-tumor and pro-tumor activities, which may be regulated in part through differential interactions with its protein partners and by its post-translational modifications." (PMID 35406615, 2022). "Thus, the outcome of RBM24-regulated p63 mRNA stability on the expression TAp63 and ΔNp63 isoforms as well as the consequence on tumor development merit further investigation." (PMID 35406615, 2022). "Moreover, RBM24 can mediate the tumor suppressor function of ncRNAs by activating apoptotic tumor cell death." (PMID 35406615, 2022). "This suggests that RBM24 has potential tumor suppressor function." (PMID 35406615, 2022).
tumor (continued). "However, MMP‐2 and MMP‐9 expression in tumour tissues were significantly upregulated and both were negatively correlated with RBM24 expression; P21 expression was inversely correlated with MMP‐2/MMP‐9 expression." (PMID 34709758, 2021). "Xenograft tumour model, Rbm24 knockout and Apcmin/+ mouse models were utilised." (PMID 34709758, 2021). "In light of the correlation between RBM24 expression and tumor stage, we speculated that RBM24 may be involved in cell proliferation." (PMID 34021255, 2021). "Previous studies have indicated that RBM24 can bind several tumour‐related genes." (PMID 34709758, 2021). "There is accumulating evidence that Rbm24 displays tumor repressive activity." (PMID 32806768, 2020). "In vitro functional assays were performed to investigate the tumor suppressive role of RBM24." (PMID 27584791, 2016). "Overall, these findings suggest a novel role of RBM24 as a tumor suppressor." (PMID 27584791, 2016). "In summary, we identified RBM24 as a novel tumor suppressor in NPC." (PMID 27584791, 2016). "However, upregulation of RBM24 in other cancers appears to promote tumor growth." (PMID 35406615, 2022). "Our study investigated the links between RBM24 expression and TGFβ-induced EMT, given the significance of EMT in tumor metastasis and former research showing that RBM24 overexpression could upregulate E-cadherin expression but downregulate Vimentin expression in HCT116 human CRC cells." (PMID 36213838, 2022). "Moreover, the tumor suppressor function of RBM24 appears to be mediated by miR-25, which is the most upregulated miRNAs in RBM24-induced cells and suppresses NPC progression by targeting the oncogenic lncRNA MALAT1 (metastasis associated with lung adenocarcinoma transcript 1) for degradation." (PMID 35406615, 2022). "Importantly, RBM24 may act as a tumor suppressor or as an oncogene in a context- or background-dependent manner." (PMID 35406615, 2022). "In addition, RBM24 overexpression restrained tumour growth and lung metastasis in vivo." (PMID 34709758, 2021). "In addition, identifying whether RBM24 plays a role as a tumor suppressor in other human malignancies will be of great interest." (PMID 27584791, 2016). "The downregulation of RBM24 in NPC suggests that it might function as a novel tumor suppressor." (PMID 27584791, 2016). "Mechanistically, RBM24 promotes the accumulation of PTEN protein, a tumor suppressor and a negative regulator of PI3K (phosphoinositide 3-kinase) signaling, by directly binding to the 3′-UTR and increasing the stability of PTEN mRNA." (PMID 35406615, 2022). "On the other hand, the increased expression of other RBP-coding genes such as RBM24 and MBNL2 (muscleblind-like 2) in CMS4 tumors and in EpCAMlo cells is in sharp contradiction with their alleged tumor suppressing roles in colon and other cancers." (PMID 36346211, 2022). "Screening for circulating tumor DNA from peripheral blood is low invasive and provides fast results, and we suggest screening for HPVP HNSCC using a panel, including RBM24, INHBA, SYCP2, TAFL7, and ZFR2." (PMID 36142875, 2022). "Notably, ROC curves showed that RBM24 level could distinguish tumours from normal tissues." (PMID 34709758, 2021). "RBM24 exerts a tumour suppressive role in CRC and targeting RBM24 holds strong promise for CRC diagnosis and treatment." (PMID 34709758, 2021).
tumor (continued). "In this study, we found that Rbm24, PTEN and P21 mRNA levels were significantly downregulated in tumour tissues of Apcmin/+ mice compared to adjacent normal samples (N = 18); meanwhile, the expression levels of MMP‐2 and MMP‐9 were markedly elevated." (PMID 34709758, 2021). "Using hybrid-PCR, a cDNA library was first produced to screen the candidate host mRNA targets for miR-M2-5p and two host genes RBM24 and MYOD1, known for their important roles in tumor induction, were identified as its biological targets." (PMID 33224130, 2020). "RBM24 was significantly downregulated in the tumor tissues and NPC cells compared with the non-tumor tissues and immortalized NPEC1 Bmi-1 cells, respectively." (PMID 27584791, 2016). "Large-scale analysis of transcriptome alterations indicates that RBM24 expression is frequently downregulated in HCC, which may trigger or sustain an undifferentiated state of tumor cells." (PMID 35406615, 2022). "RBM24 expression also appears to be dysregulated in several other cancer types, but functional and molecular analyses of its activity in tumor progression are still lacking." (PMID 35406615, 2022). "Statistical analyses indicted that the tumor incidence for Rbm24+/− mice was not significantly different from that for WT mice (p = 1.0 by Fisher’s exact test), but less than Rbm38−/− mice (p = 0.0227 by Fisher’s exact test)." (PMID 36478739, 2022). "In addition, RBM24 expression in tumour tissues of CRC patients was dramatically reduced and the expression of RBM24 correlated significantly with the prognosis of CRC patients, which was consistent with the data from TCGA and GEPIA databases." (PMID 34709758, 2021). "Combined with the data obtained from miRNA-overexpressing and virus-infected cells, we finally identified the host RBM24 and MYOD1 genes as two biological targets for miR-M2-5p, which have been frequently reported as important tumor suppressors in previous studies." (PMID 33224130, 2020). "In other situations, the tumor suppressor activity of Rbm24 does not seem to be dependent on its phosphorylation." (PMID 32806768, 2020). "In addition, similar results were obtained from correlation analysis among the expression levels of RBM24, miR-25, and MALAT1 in the primary NPC fresh tumor tissues." (PMID 27584791, 2016).